MTAP (methylthioadenosine phosphorylase)
Diseases named in the same sentence as MTAP in open-access papers (continued):
Sharing a sentence is not in itself a finding about the gene and the disease.
cancer (continued). "In MTAP deleted cancers, PRMT5 and methionine adenosyltransferase II α (MAT2A) enzymes were identified as synthetic lethal targets." (PMID 34573422, 2021). "Since the loss of MTAP leads to the accumulation of MTA, an endogenous PRMT5 inhibitor, GSK3368715 can be effective in MTAP-null cancer cells by mediating the blockage of the compensatory relationship between ADMA and SDMA107." (PMID 34006904, 2021). "Due to its genomic proximity to the tumor suppressor genes CDKN2A and CDKN2B, the MTAP gene is commonly co-deleted in human cancer." (PMID 33691794, 2021). "Despite being an anti-cancer target, MTAP is genomically deleted in 15% of human cancers together with the neighboring CDKN2A, one of the most frequently deleted tumor suppressor genes in human cancers." (PMID 33893330, 2021). "Therapeutic targeting of PRMT5 in homozygous MTAP-deleted cancer cells has thus been considered a promising strategy to prevent methylosome organization, selectively killing cancer cells." (PMID 34244484, 2021). "First, we measured the SDMA levels in MTAP-WT and MTAP-deleted cancer cells in culture (under the same conditions in which we measured MTA accumulation in media) by western blot analysis." (PMID 34244484, 2021). "MTAP-deleted cancer cells accumulate methylthioadenosine (MTA), which inhibits the methyltransferase activity of protein arginine methyltransferase 5 (PRMT5)." (PMID 34526971, 2021). "The downstream inhibition of PRMT5 is similar to the effects of a MAT2A inhibitor in an MTAP−/− cell line, in that both inhibit cancer cell growth via restriction of PRMT5 activity." (PMID 33893330, 2021). "Due to the intracellular accumulation of methylthioadenosine (MTA), an endogenous PRMT5 antagonist, MTAP deletion renders cancer cells sensitive to PRMT5." (PMID 34006904, 2021). "Based on this rationale, the combination of a PRMT1 inhibitor and PRMT5 inhibitor synergistically inhibits the proliferation of cancer cells with MTAP deletion." (PMID 34006904, 2021). "The ubiquity of this event alongside the poor prognosis of cancers such as GBM has urged the development of novel therapies that capitalize on downstream vulnerabilities conferred by MTAP deletion." (PMID 34244484, 2021). "That MTAP deletions can be leveraged as a point of selective vulnerability in various cancers has spurred much excitement." (PMID 34244484, 2021). "The MAT2A inhibitor AG-270 applied to MTAP−/− cancer cells inhibits SAM production, together with increased MTA resulting in decreased SDMA levels as its mechanism of action." (PMID 33893330, 2021). "A prime example is MTAP, the rate limiting enzyme in the methionine salvage pathway, which is deleted in a variety of cancers along with the neighboring tumor suppressors CDKN2A and ARF." (PMID 34109280, 2021). "We earlier discussed the discrepancies in the magnitudes of reported MTA between MTAP-deleted and MTAP-WT cancer cell lines." (PMID 34244484, 2021). "Our findings indicate that MTAP-WT cells in the vicinity of MTAP-deleted cancer cells prevent extracellular accumulation of MTA." (PMID 34244484, 2021). "Patient M1 had three variants in cancer-related genes (PRKAR1A c.221G>A; COL7A1 c.7313C>G; and MTAP c.634T>C)." (PMID 32443704, 2020). "Other cancer-related genes, such as COL7A1, PRKAR1A, ERCC3, and MTAP, had variants with a conflicting interpretation of pathogenicity or VUS, or they were not reported in ClinVar." (PMID 32443704, 2020). "Normal cells or cancers with intact MTAP, and thus high flux through the methionine salvage pathway, are less sensitive to PRMT5 inhibition." (PMID 32276408, 2020). "Our NanoString Pan-Cancer Panel analysis of MTAP gene-edited cell lines showed a significantly altered expression of genes associated with RAS/MAPK/PI3K-AKT and apoptosis pathways after MTAP gene knockout." (PMID 32093414, 2020).
cancer (continued). "The enzyme methylthioadenosine phosphorylase (MTAP) plays a major role in the metabolism of polyamines and its deficiency has been implicated in the response of cancer cells to 6-TG." (PMID 31284411, 2019). "Consistent with other cancers, our bio-functional assays prove that MTAP plays an inhibitory role in oncogenic progression, particularly in cell motility and invasion." (PMID 30701095, 2019). "MTAP deletion increases dependence on protein arginine methyltransferase 5 (PRMT5) and inhibition of PRMT5 selectively kills MTAP-null cancer cells, indicating that inhibition of PRMT5 is a potential therapy for MTAP-deleted tumors." (PMID 31450721, 2019). "MTAP deletion in certain cancers has been observed for decades, but treatment for these patients has had limited success in the clinic." (PMID 30701095, 2019). "Three recent studies have reported an increased dependency of cancer cells harboring a homozygous deletion of the MTAP gene on PRMT5, WDR77 and RIOK1, all members of a PRMT5 containing complex, and the upstream component MAT2A." (PMID 29983885, 2018). "Deletion of metabolic enzyme 5-methylthioadenosine phosphorylase (MTAP) is a frequently observed phenomenon in many cancers harboring CDKN2A (p16INK4a and p14ARF) tumor suppressor gene deletion." (PMID 30613353, 2018). "It has been proposed that inhibiting the enzymatic function of PRMT5 represents a therapeutic option to treat MTAP mutant cancers." (PMID 29983885, 2018). "Three recent reports showed that an increased intracellular concentration of methylthioadenosine (MTA) in cancer cells harboring 5-methylthioadenosine phosphorylase (MTAP) deletions leads to PMRT5 inhibition." (PMID 29163371, 2017). "Three genes were located between these two lncRNA genes: IFNE, MTAP, and CDKN2A, all of which are associated with cancer." (PMID 27903974, 2017). "The MTAP locus is one of the most frequently deleted chromosomal regions in several types of human cancers due to its proximity to the CDKN2A (p16) gene on chromosome 9p21." (PMID 26910893, 2016). "MTAP is one of the genes most frequently deleted in some types of cancer, likely due to its proximity to the CDKN2A/p16 locus." (PMID 26910893, 2016). "The cancers which lose MTAP expression required methionine and cannot grow in methionine deprivation." (PMID 27579534, 2016). "The associations of the deletion of tumor suppressor genes CDKN2A, CDKN2B, and MTAP with the four significant enriched cancer types in this subgroup have been widely investigated and reported." (PMID 26148869, 2015). "Methionine can also be produced by the salvage pathway via the crucial enzyme methylthioadenosine phosphorylase (MTAP), which has been shown to be deleted in various cancers." (PMID 25880539, 2015). "Furthermore, the region at canine chromosome 11 (orthologous to human chromosome 9p21) encoding INK4A/ARF, MTAP and close neighbors including miR-31, as shown in the comparative chromosomal mapping, is also highly susceptible and prone to concomitant deletion in many cancers in dogs." (PMID 29056711, 2015). "The gene encoding the methionine salvage pathway methylthioadenosine phosphorylase (MTAP) is a tumor suppressor gene that is frequently inactivated in a wide variety of human cancers." (PMID 23840755, 2013). "Consequently, MTAP has emerged as a target for enzymatic inhibition to enable synthetic lethal strategies in the 85% of cancers that are MTAP+/+." (PMID 41825704, 2026). "Similarly, selectivity for MTAP-deleted cancer cell lines was observed, with sensitivity to AMG193 correlated with a genetic dependency on PRMT5." (PMID 40157258, 2025). "These compounds provided a proofof concept that MTAP-deleted cancers could be targetedwith MTA-cooperative PRMT5 inhibitors." (PMID 39919252, 2025).
cancer (continued). "In approximately 10-15% of human cancers, deletion of the methylthioadenosine phosphorylase (MTAP) gene results in accumulation of methylthioadenosine (MTA), exposing a synthetic lethality and opportunity for precision medicine by selective targeting of PRMT5 in this context." (PMID 41339334, 2025). "This difference in the rate of MTAP deficiency is probably due to a more rigorous exclusion of samples lacking unequivocal cancer tissue in this study." (PMID 40227771, 2025). "Methylthioadenosine phosphorylase (MTAP) gene deletions are frequent in human cancers." (PMID 40377999, 2025). "However, four molecules are already undergoing phase II clinical trials in cancer patients with MTAP gene deletion." (PMID 41465382, 2025). "BAP1 and MTAP genes are significantly involved in the development of cancer." (PMID 40506895, 2025). "Tumor infiltration by lymphocytes will be reduced in MTAP-deleted cancers." (PMID 41465382, 2025). "Co-deletion of CDKN2A and MTAP due to its proximity occurs frequently across cancers." (PMID 40627883, 2025). "Recent studies have identified that the absence of MTAP in cancer cells renders them more susceptible to PRMT5 and MAT2A depletion." (PMID 40430461, 2025). "Additionally, TNG462 was assessed in the same 7-day viability assay usinga 179-cancer cell line panel representing multiple lineages and showedan median 41-fold selectivity for MTAP-null cell lines relative toMTAP WT cell lines." (PMID 40035511, 2025). "To elucidate the molecular mechanisms by which MTAP regulates antitumor immune responses, we performed bulk RNA sequencing to analyze transcriptomic alterations in MTAP-WT (WT) and MTAP-KO (KO) cancer cells co-cultured with peripheral blood mononuclear cells (PBMCs) (WT+PBMC and KO+PBMC)." (PMID 41246302, 2025). "Surprisingly, MAT2A inhibition exhibits a gratifying result in the MTAP-deleted cancers." (PMID 41445748, 2025). "The virtual independency of the adenine requiring proliferative activity of ERG positive tumor cells from MTAP expression levels might suggest that the MTAP dependent salvage pathway for adenine synthesis has reduced importance in these cancers." (PMID 40554389, 2025). "MTAP also plays a role in regulating the cell lineage and morphology in different cancers." (PMID 41439984, 2025). "The inhibition of methionine adenosyltransferase 2A (MAT2A) in cancers harboring deletions of the methylthioadenosine phosphorylase (MTAP) gene induces synthetic lethality, making it a highly compelling strategy in the pursuit of precision anticancer therapeutics." (PMID 40430308, 2025). "A comparison with clinico-pathological features revealed inverse correlations depending on the ERG fusion status: In ERG-negative cancers, high (3+) MTAP expression correlated with advanced pT stage, high Gleason grade, and early PSA recurrence (p < 0.0001 each)." (PMID 40554389, 2025). "Moreover, numerous studies reveal that the CDKN2A locus (encodes the tumor suppressor p16) on chromosome 9p21 is frequently lost in 15% of all cancer cell subsets, and interestingly, the adjacent MTAP locus is co-deleted in 80-90% of these cancer cells." (PMID 41445748, 2025). "Notably, MAT2A is essential for the survival of cancers harboring deletions of the methylthioadenosine phosphorylase (MTAP) gene, which occurs in approximately 13–15% of tumors due to its co-deletion with the CDKN2A tumor suppressor." (PMID 40430308, 2025). "Consequently, MTAP deleted cancers are particularly vulnerable to further inhibition with second-generation PRMT5 inhibitors that can selectively target the PRMT5:MTA complex leading to a synthetic lethal relationship." (PMID 40823091, 2025). "In cancer patients, the presence of MTAP deletion is a negative prognostic factor associated with shortened overall survival (OS)." (PMID 41465382, 2025).
cancer (continued). "The durable PD hold by TNG462 observed in vivo was supported by an in vitro studydemonstrating that TNG462 conferred strong thermostabilityto cellular PRMT5 even after compound had been removed for 72 h ina washout study using the LN18 MTAP-null cancer cell line." (PMID 40035511, 2025). "This study introduces a broadly applicable method for directed DNA-encoded library screening toward a desired mechanistic outcome and highlights MTA-selective PRMT5 inhibition as an attractive therapeutic strategy with a potentially broad therapeutic index in patients with MTAP-deleted cancers." (PMID 40377999, 2025). "We performed IHC in a case of CRC harbouring MTAP loss: although there was minimal heterogeneity in staining, 90%–98% of cancer cells did not express MTAP protein, as compared with intense and homogeneous protein expression in proficient cases." (PMID 38350716, 2025). "Recent studies have found that regulating the activity of MAT2A may provide a new strategy for the treatment of MTAP deletion cancer." (PMID 40240755, 2025). "Because MTAP is closely associated to polyamine biosynthesis, recycling of SAM and the regulation of inhibitory MTA levels, it has also been proposed as a target for cancer therapy." (PMID 40375736, 2025). "We reasoned that compounds that preferentially inhibit PRMT5 in the presence of MTA might constitute an attractive modality to treat MTAP-deleted cancers with less adverse effects on normal tissues." (PMID 40377999, 2025). "The methylthioadenosine phosphorylase (MTAP) gene is recurrently lost in human cancers." (PMID 40377999, 2025). "Therapeutic targeting of PRMT5 in homozygous MTAP‐deleted cancer cells has thus been considered a promising strategy to selectively killed cancer cells, which predicated on the presence of exceedingly high MTA levels in MTAP‐deleted cancer cells compared to MTAP‐intact tissues." (PMID 39711357, 2024). "It has demonstrated potent anti-tumor activity in MTAP-null cancer cell lines and tumor xenograft models and will be further studied in a first-in-human phase I/II trial in patients with advanced solid tumors with confirmed MTAP deletion (NCT05094336)." (PMID 39337530, 2024). "Furthermore, the combination of SCR‐7952 with SAM‐competitive or MTA‐cooperative PRMT5 inhibitors supported further investigation and potential development of an effective strategy for larger therapeutic windows on MTAP‐deleted cancers." (PMID 39309689, 2024). "Consequently, the formation of PRMT5-MTA complexes sensitizes MTAP-deleted cancer cells to enable further PRMT5 inhibition." (PMID 38610930, 2024). "PRMT5 has emerged as a synthetically lethal drug target for the treatment of MTAP-deleted cancers." (PMID 39337530, 2024). "Consequently, in MTAP−/− tumors the synthetic lethal inhibition of MAT2a ultimately converges on PRMT5 inhibition that reduces cancer growth and induces cell death." (PMID 38000655, 2024). "For example, MTAP (encoding methylthioadenosine phosphorylase) is located in proximity to the tumor suppressor gene CDKN2A in the genome and thus often co-deleted with CDKN2A in cancer cells." (PMID 38638566, 2024). "The potential role and impact of MTAP-loss as a therapeutic target in advanced gastrointestinal (GI) cancers have not yet been directly interrogated." (PMID 38330461, 2024). "It should be noted that MTAP could also be inactivated by promoter hypermethylation in cancer, which indicates epigenetic alterations in MRGs could feed back and modulate methionine metabolism." (PMID 37179124, 2023). "Additionally, since MTAP is frequently deleted in human cancers due to its proximity to the tumor suppressor gene CDKN2A, the therapeutic potential of type I PRMT inhibition alone merits investigation." (PMID 37237172, 2023). "MTA accumulation in MTAP deleted cells creates a hypomorphic PRMT5 state that is sensitized towards further PRMT5 inhibition making PRMT5 inhibitors a potential therapy for MTAP deleted cancers." (PMID 36913304, 2023).
cancer (continued). "TNG908 demonstrated a 15-fold higher potency in MTAP-null cancer cell lines." (PMID 38136401, 2023). "MTAP deficiency commonly occurs in hematological malignancies and various solid tumors, suggesting that MTAP may play a tumor-suppressing role in these types of cancer." (PMID 36831453, 2023). "Identifying the major substrates of PRMT5 that are still methylated in MTAP-deleted cancers may be important to understanding what reactions PRMT inhibitors are acting on in these cancers." (PMID 38134182, 2023). "Approximately 15% of cancers exhibit loss of the chromosomal locus 9p21.3 – the genomic location of the tumour suppressor gene CDKN2A and the methionine salvage gene methylthioadenosine phosphorylase (MTAP)." (PMID 37795443, 2023). "Importantly, MAT2A inhibitors have anti-proliferative activity in MTAP-deleted cancer cells and tumors, a result that prompted the development of a phase I clinical trial using MAT2A inhibitors (ClinicalTrials.gov NCT03435250)." (PMID 35631199, 2022). "It is overexpressed in various human cancers, and its inhibition causes cell death, especially in cancer cells lacking 5′-methylthioadenosine phosphorylase (MTAP)." (PMID 36192627, 2022). "MTAP is a clinically relevant enzyme in the treatment of cancer since the reaction it mediates is also key for purine nucleotide salvage that is over-activated in cancer cells." (PMID 35383287, 2022). "The MTAP SNP reference allele frequency was 53%, 78%, and 63% in the no cancer, HS, and other cancer groups, respectively." (PMID 36292578, 2022). "It led to the development of a different class of substrate-competitive inhibitors that preferentially bind the PRMT5:MEP50 complex with MTA and may be used to pharmacologically exploit the PRMT5-related vulnerability in MTAP−/− cancer cells." (PMID 36192627, 2022). "Inactivation of MTAP, often by homozygous deletion, is found in both solid and hematologic malignancies and is one of the most frequently observed genetic alterations in human cancer." (PMID 35963436, 2022). "Identification of those symmetrically dimethylated proteins with reduced sDMA levels required for the malignancy of MTAP‐deleted cancers may provide an opportunity for tailored cancer therapy." (PMID 35766227, 2022). "CDKN2A and MTAP were ~100 kb apart on 9p21.3 and commonly co-deleted in human cancers." (PMID 34556668, 2021). "Here, the authors show that MTA does not accumulate in MTAP-deficient cancer cells but is secreted and metabolized by MTAP-intact cells in the tumour microenvironment." (PMID 34244484, 2021). "Thus, inhibition of MTAP in cancers by a specific inhibitor has potential as a sole agent and as an enhancer of new agents designed to target histone, DNA, and intron methylation." (PMID 33893330, 2021). "MTDIA causes a physiologic inactivation of MTAP and may also have efficacy in combination with inhibitors of MAT2A or PRMT5, known synthetic-lethal interactions in MTAP−/− cancer cell lines." (PMID 33893330, 2021). "Interestingly, MTAP-deleted cancer cells accumulate the metabolite methylthioadenosine (MTA), which is a high-affinity inhibitor of PRMT5 activity." (PMID 33691794, 2021). "Finally, the mechanism of action of MTDIA was investigated by assessing PRMT5 activity in treated mice and by generation of an MTAP inhibitor-resistant cell line of FaDu cancer cells, revealing amplification of MAT2A, a known target in MTAP−/− cancers." (PMID 33893330, 2021). "The physiologic impact of MTDIA on tissue metabolite levels and arginine methylation were also determined, since elevated MTA can potentially interact with other targets including type 1 PRMTs, PRMT5 and MAT2A by mimicking the metabolic physiology observed in MTAP−/− cancer cell lines." (PMID 33893330, 2021). "Therefore, MTA accumulation due to MTA phosphorylase (MTAP) deletion has been proposed as a vulnerability for PRMT5-targeted therapy in cancer." (PMID 34244484, 2021).